STAT3 (signal transducer and activator of transcription 3)
Diseases named in the same sentence as STAT3 in open-access papers (continued):
Sharing a sentence is not in itself a finding about the gene and the disease.
cholangiocarcinoma (77 papers, 2009 to 2025). A carcinoma that arises from the intrahepatic biliary tree (intrahepatic cholangiocarcinoma) or from the junction, or adjacent to the junction, of the right and left hepatic ducts (hilar cholangiocarcinoma). "For instance, in cholangiocarcinoma, IL‐6 inhibition has been shown to counteract gemcitabine resistance by suppressing STAT3 activation driven by IL‐6–producing cancer‐associated fibroblasts." (PMID 41189442, 2025). "Lan C caused a decrease in the protein expression of STAT3 in cholangiocarcinoma cells, which inhibited the classical STAT3 pro-cancer pathway and led to apoptosis of cancer cells." (PMID 37397486, 2023). "Signal transducer and activator of transcription 3 (STAT3) is a key mediator of the oncogenic effects caused by EGFR signaling in cholangiocarcinoma." (PMID 32365487, 2020). "Chronic inflammation is a known risk factor for the development of cholangiocarcinoma; STAT3 is involved in signaling pathways associated with inflammation, and its activation may contribute to the inflammatory microenvironment that promotes tumorigenesis." (PMID 40426911, 2025). "Furthermore, expression of STAT3 is associated with poor histological differentiation and adverse prognosis in patients with cholangiocarcinoma." (PMID 29029413, 2017). "To determine STAT3 expression in cholangiocarcinoma, we downloaded and analyzed data from the TGCA cohort bile duct cancer CHOL (n = 45; 36 primary tumor and 9 normal tissue samples) from the platform XENA." (PMID 40426911, 2025). "The direct interaction between CGGNBP2-184aa and STAT3 promotes STAT3Tyr705 phosphorylation and plays a positive regulatory role in regulating IL-6/STAT3 signaling, promoting intrahepatic cholangiocarcinoma cell proliferation and metastasis." (PMID 40034125, 2025). "In cholangiocarcinoma tumor cells, the binding of STAT3 to the m6A writer gene results in the upregulation of m6A writers by cytokine IL-6, suggesting that m6A is a potential target in response to inflammation." (PMID 39136000, 2024). "A recent study reported a highly promising approach from targeted STAT3 for the treatment of CCA (cholangiocarcinoma)." (PMID 38397805, 2024). "Tumor immunohistochemistry showed that nude mice transplanted with human cholangiocarcinoma cells treated with Lan C exhibited decreased STAT3 expression and increased caspase-9 and caspase-3 expression in tumors, consistent with the in vitro results." (PMID 37397486, 2023). "In our study, sequencing and network pharmacology analysis suggested that STAT3 represents a poteneially important target of Lan C action on cholangiocarcinoma cells, confirmed in subsequent WB and in vivo experiments." (PMID 37397486, 2023). "In the present study, the action of Lan C on cholangiocarcinoma cells increased intracellular ROS production and inhibited the pro-oncogenic function of the transcription factor STAT3." (PMID 37397486, 2023). "β-Caryophyllene has been reported to down-modulate STAT3 signaling, thus chemosensitizing cholangiocarcinoma cells to doxorubicin or sorafenib treatment." (PMID 35956786, 2022). "JAK/STAT3 signaling is constitutively activated in cholangiocarcinoma and represents an important target for treating this disease." (PMID 35790790, 2022). "On the other hand, STAT3 hyperactivation [as in cholangiocarcinoma (CCA)] determines an epigenetic silencing of the SOCS3 gene and cellular resistance to apoptosis and induction of EMT." (PMID 35047557, 2021). "For cholangiocarcinoma, G1-phase cell cycle arrest was demonstrated with berberine, an alkaloid from Berberis vulgaris and Berberis aquifolium via NF-κB and STAT3 pathways." (PMID 32212786, 2020). "AURKA inhibition is attractive in cholangiocarcinoma as it has been shown to interact with and control a variety of proteins that play key roles in cholangiocarcinoma pathogenesis such as STAT3 36 and Mcl-122." (PMID 32127951, 2020).
cholangiocarcinoma (continued). "Among them, curcumin exhibited anti-cholangiocarcinoma effects by the suppression of different transcription factor cascades, among which STAT3, NF-kB and AP-1." (PMID 32252311, 2020). "Regarding cholangiocarcinoma, leptin was found to increase the proliferation and metastatic potential of cholangiocarcinoma cells through STAT3-dependent activation of ERK 1/2." (PMID 33167521, 2020). "Cryptotanshinone, a natural active compound of S. miltiorrhiza Bunge, has been shown to affect cell cycle arrest and apoptosis through the PI3K/Akt/NFκB and JAK2/STAT3 pathways in cholangiocarcinoma cells." (PMID 31406500, 2019). "Constitutive STAT3 activation in cholangiocellular carcinomas has previously been shown to be centrally involved in regulating oncogenic gene transcription, tumor progression, and resistance to apoptosis." (PMID 30949204, 2019). "Previous studies have shown that IL-6-induced Stat3 signaling upregulates Mcl-1 transcription in cholangiocarcinoma cells." (PMID 29899555, 2018). "Downregulation of this miRNA cluster was recently shown to induce tumorigenesis due to a loss of inhibition of key inflammatory cytokines involved in the IL-6/signal transducer and activator 3 (STAT3) pathway in cholangiocarcinoma." (PMID 28208661, 2017). "In STAT3 overexpressing cholangiocarcinoma cells, inhibition of p-STAT3 after SC-43 treatment was reduced." (PMID 29029413, 2017). "Generally, IL-6 was secreted by noncancer stem cells in low-attachment culture conditions and enriched Oct4 gene expression by activating the IL-6R/JAK/STAT3 signaling pathway in chronic inflammatory disease, such as cholangiocarcinoma." (PMID 27809873, 2016). "In conclusion, autocrine and paracrine LIF signaling promote chemoresistance in cholangiocarcinoma by up-regulating Mcl-1 via a novel STAT3- and MAPK-independent, PI3K/AKT-dependent pathway." (PMID 26296968, 2015). "IL-6, which has been shown to activate Mcl-1 transcription in PCa and cholangiocarcinoma cells through a signal transducer and activator of transcription 3 (Stat3)-dependent mechanism, was included as the positive control." (PMID 22276222, 2012). "For example, interleukin-6, an inflammatory cytokine, promotes human cholangiocarcinoma cells grown in vivo by inhibiting apoptosis through the activation of miRNAs including miR let-7a and miR370, thereby modulating the activation of STAT-3 pathways." (PMID 19436294, 2009). "In human cholangiocarcinoma, sustained IL-6/Stat3 signalling, enhanced Mcl-1 expression and resistance to apoptosis, is attributed to epigenetic silencing of SOCS3 by promoter hypermethylation." (PMID 19698101, 2009). "Aberrant activation of STAT3 has been observed in several cancers, including cholangiocarcinoma." (PMID 40426911, 2025). "Evodiamine inhibits the proliferation and induces apoptosis of cholangiocarcinoma cells, inhibits the migration and invasion of cholangiocarcinoma cells, suppresses IL-6/STAT3 signal transduction by upregulating the expression of SHP-2, and treats cholangiocarcinoma." (PMID 39944619, 2025). "Additionally, in this case, Sorafenib-induced dephosphorylation of Tyr705 STAT3 is mediated by SHP2, and in cholangiocarcinoma cells, Sorafenib-induced dephosphorylation of Tyr705 p-STAT3 is inhibited by knocking down SHP2." (PMID 38504984, 2024). "Various cancers, including cholangiocarcinoma, frequently exhibit STAT3 activation." (PMID 37397486, 2023). "We demonstrated that Lan C inhibits the growth of cholangiocarcinoma cells and promotes their apoptosis by increasing ROS production, decreasing mitochondrial membrane potential and inhibiting the pro-oncogenic effect of STAT3." (PMID 37397486, 2023). "Thus, our study reveals a unique approach to target STAT3 via ROS-induced anticancer compounds, providing a promising avenue for treating cholangiocarcinoma." (PMID 37397486, 2023). "We also used an STAT3 inhibitor, cryptotanshinone, to treat cholangiocarcinoma cell lines." (PMID 34440089, 2021).
cholangiocarcinoma (continued). "Similarly, we highlighted a STAT3 phosphorylation at Tyr705 due to doxorubicin treatment in cholangiocarcinoma cells, thus confirming its role as a chemoresistance mediator." (PMID 33081075, 2020). "The result suggests that the combination of Huaier with 5-FU had a synergistic antitumor effect in proliferation, apoptosis, cell cycle and motility of cholangiocarcinoma cells; STAT3 pathway might be a potential target." (PMID 31391034, 2019). "STAT-3 dephosphorylation induced by Sorafenib has been described in in vitro studies of human medulloblastomas and esophageal adenocarcinomas, and in vivo study of cholangiocarcinomas." (PMID 29464101, 2018). "Moreover, sorafenib inhibits STAT3 signaling in cholangiocarcinoma cells (CCA) by activating SHP229." (PMID 29242509, 2017). "A recent study showed miR-17–92 was regulated by IL-6/STAT3 in cholangiocarcinoma cells." (PMID 29254202, 2017). "Furthermore, we found that ABC294640 inhibited STAT3 phosphorylation, one of the key signaling pathways regulating cholangiocarcinoma cell proliferation and survival." (PMID 26956050, 2016). "Interleukin 6 (IL-6)-mediated signal transducers and activators of transcription 3 (STAT-3) phosphorylation (activation) is aberrantly sustained in cholangiocarcinoma cells resulting in enhanced myeloid cell leukemia 1 (Mcl-1) expression and resistance to apoptosis." (PMID 25344679, 2014). "In a study by Chen and colleagues, allicin (40 μM) was found to inhibit the proliferation and invasion of cholangiocarcinoma (CCA) cells by targeting STAT3, a key transcription factor involved in cell proliferation." (PMID 39272454, 2024). "Similarly, myricetin treatment potently inhibited the cytokine-induced migration and invasion of KKU-100 cholangiocarcinoma cells, mediated partially through STAT3 suppression; myricetin also suppressed downstream target genes of STAT3, including ICAM-1, MMP-9, iNOS, and COX-2." (PMID 34950252, 2021). "According to in vivo research, allicin 10 and 20 mg/kg was administered, i.e., daily for 4 weeks, and it increased the apoptotic caspases that were produced in Cholangiocarcinoma (CCA) by suppressing STAT3 signalings, such as cleaved caspase-3 and cleaved caspase-9." (PMID 38542956, 2024). "In cholangiocarcinoma, as mentioned, TAN/TAM co-cultures produce high levels of OSM (TANs) and IL-11 (TAMs), which activate the STAT3 signaling pathway in iCCA cells, sustaining invasiveness." (PMID 36077744, 2022). "For example, IL-6/STAT3-induced miR-17–92 targets JAK/STAT3 pathway inhibitor SOCS3 and PIAS3, generating a positive feedforward loop that amplifies IL-6/STAT3 signaling and contributes to cholangiocarcinoma cell proliferation and invasion." (PMID 35842651, 2022). "Furthermore, EGCG with quercetin can block the JAK/STAT pathway, ultimately making STAT1 and STAT3 inactive in cholangiocarcinoma (CCA) cells." (PMID 36193062, 2022). "In vitro, conditioned medium from cholangiocarcinoma cell lines (HuCCT1, RBE and MEC) induced activation of STAT3 in modeled TAMs and enhanced production of IL-10, VEGF-α, TGF-β and MMP-2 in CD163+ TAMs." (PMID 36686729, 2022). "ESR1 significantly impacts the prognosis of iCCA patients and markedly suppresses cholangiocarcinoma cell proliferation, migration and invasion by inhibiting JAK/STAT3 signaling pathway." (PMID 33865377, 2021). "Among cholangiocarcinoma patient specimens, specimens with higher levels of phosphorylated STAT1 and STAT3 exhibited higher ALDH1A3 expression and vice versa." (PMID 34440089, 2021). "Signal transducer and activator of transcription 3 (STAT3) is considered an oncogene, being continuously activated in more than 50% of human solid tumor (e.g. Cholangiocarcinoma)." (PMID 31391034, 2019).
cholangiocarcinoma (continued). "After NAC pretreatment, STAT3 expression was not downregulated in cholangiocarcinoma cells, the expression of p-STAT3 was significantly increased compared with Y3 group, and caspase-3, caspase-9, cleaved PARP expression were significantly inhibited." (PMID 37397486, 2023). "As a previous study indicated that STAT3 could bind to the promoter region of ALOX5 in cholangiocarcinoma, we started to determine whether PIK3CAmut stimulated 5‐LOX expression by regulating the phosphorylation of Akt and STAT3 in vitro." (PMID 37965796, 2023). "It is noteworthy that a basal phospho(Tyr705)-STAT3 was found expressed in Mz-ChA-1 cholangiocarcinoma cells compared the noncancerous H69 cholangiocytes, thus confirming that the upregulation of this signaling is a typical feature of cancer cells." (PMID 32252311, 2020). "Accordingly, the compound blocked the increased levels of phosphor (Tyr705) STAT3 induced by doxorubicin in both cholangiocarcinoma and noncancerous cholangiocytes." (PMID 33081075, 2020).
ischemic stroke (77 papers, 2013 to 2026). A stroke disorder caused by obstruction of blood flow to the brain, due to thrombotic (local blood clot formation) or embolic (due to a blood clot or other material traveling from another site) event. "In a murine model of ischemic stroke, the beneficial effects on neuronal death and axonal remodeling of colivelin have also been associated with activation of STAT3 signaling." (PMID 36119052, 2022). "Its protective role is mediated through the inhibition of apoptosis and inflammatory responses via the JAK2/STAT3 axis, suggesting its potential as a therapeutic target for ischemic stroke." (PMID 41906531, 2026). "Research shows that melatonin modulates the polarization of microglia towards M2 type via the STAT3 signaling pathway in ischemic stroke treatment." (PMID 40715012, 2025). "Currently, there is still controversy regarding the impact of STAT3 on microglial polarization during ischemic stroke." (PMID 37869777, 2024). "Remarkably, knockdown of circPTP4A2 in ischemic stroke promoted a phenotypic transformation of microglia from an M1 to an M2 state, potentially mediated by the downregulation of phosphorylated STAT3." (PMID 37869777, 2024). "In another study about experimental ischemic stroke, secretoneurin protected neurons against hypoxic injury obviously by activating vascular regeneration Jak2/Stat3 pathway." (PMID 39002049, 2024). "Mechanistically, circPTP4A2 regulates microglial polarization in response to ischemic stroke by binding to STAT3 and modulating its phosphorylation activation, as revealed by our study." (PMID 37869777, 2024). "Further investigation is warranted to elucidate the underlying molecular mechanisms by which circPTP4A2 modulates the cytoplasmic/nuclear translocation of STAT3 in microglia following ischemic stroke." (PMID 37869777, 2024). "On the contrary, a recent study demonstrated that IL‐13 promoted the polarization of microglia toward the M2 phenotype by inhibiting STAT3 phosphorylation after ischemic stroke." (PMID 37869777, 2024). "Accumulating evidence has demonstrated that STAT3 activation mediates pro‐inflammatory responses in microglia during ischemic stroke." (PMID 37869777, 2024). "IL-6, AKT1, VEGFA, STAT3, TNFα, etc., were the core target of phenolic acids in preventing ischemic stroke." (PMID 36778026, 2023). "Our findings suggest that EP contributes to attenuating neuronal apoptosis, Th17/Treg imbalance, and inflammation induced by MCAO via inhibiting the JAK2/STAT3 pathway, indicating its therapeutic potential in ischemic stroke." (PMID 37143406, 2023). "STAT3 is closely related to ischemic stroke and ischemia–reperfusion injury, and its high expression aggravates nerve damage." (PMID 37077541, 2023). "Previous research has shown that administering recombinant human Osm to mice before the initiation of ischemia/reperfusion can improve prognosis in mouse models of ischemic stroke by activating the JAK2/STAT3 signaling pathway in neurons." (PMID 36875640, 2023). "Studies have found that phosphorylated-STAT3 (p-STAT3) is predominantly localized in microglia/macrophages in the post-ischemic brain with increases 6–72 h after ischemic stroke." (PMID 35578342, 2022). "Inhibition of p-STAT3 is involved in the microglia/macrophages polarization, white matter repair and long-term neuronal protection provided by IL-13 after ischemic stroke." (PMID 35578342, 2022). "The neuroprotective and pro-angiogenic activities of ahNSCs were mediated by paracrine factors and involved the JAK2/STAT3 signaling pathway in in vitro and in vivo ischemic stroke models in this study." (PMID 36446389, 2022). "Phosphorylation of STAT3 modulates microglia/macrophage polarization and inhibits neuronal apoptosis and autophagy through STAT3-mediated effects in ischemic stroke." (PMID 36188543, 2022).